LINC01812 (long independently transcribed non-coding RNA 1812)
Gene: Long non-coding RNA gene on chromosome 2 (67,796,047 to 67,825,658, reverse strand). Ensembl gene ENSG00000237013.
Diseases named in the same sentence as LINC01812 in open-access papers:
LINC01812 is named in the same sentence as 1 disease in open-access papers, as found by Europe PMC text mining. Sharing a sentence is not in itself a finding about the gene and the disease. The quoted sentences say what the papers report.
tumor (1 paper, 2025). "Recent findings reveal that LINC01812 is significantly upregulated in tumor tissues and is selectively packaged into tumor-derived exosomes." (PMID 40980689, 2025). "Additionally, lncRNA LINC01812 has emerged as a critical regulator in the tumor microenvironment of CCA." (PMID 40980689, 2025).